AQP3 (aquaporin 3 (Gill blood group))
Diseases named in the same sentence as AQP3 in open-access papers (continued):
Sharing a sentence is not in itself a finding about the gene and the disease.
colitis (17 papers, 2008 to 2025). Inflammation of the colon. "A previous study showed that AQP3-deficient mice have lower cell proliferation and more severe colitis compared with wild-type mice." (PMID 35955466, 2022). "It was shown that activation of ERK is not only engaged in enhancing and maintaining visceral sensitivity, but is also associated with increased intestinal MUC2 expression in colitis mice by allyl isothiocyanate, and accompanied by downregulation of colonic AQP3 in an IBS model." (PMID 38634140, 2024). "Interestingly, the AQP3-deficient mice displayed a reduced cell proliferation of enterocytes and developed severe colitis, probably due to an impaired transport of glycerol for maintaining normal production of ATP energy." (PMID 38089478, 2023). "Mice with AQP3 gene knockout in DSS-induced colitis exhibited more severe colon pathology and a reduced survival rate compared to wild-type mice." (PMID 40093802, 2025). "With oral glycerol administration, these symptoms were reversed by significantly improving survival and reducing the severity of colitis, revealing the important role of AQP3 in enterocyte proliferation due to its glycerol-transporting function." (PMID 35187089, 2022). "In fact, oral glycerol administration largely enhanced survival of AQP3 null mice and reduced the severity of colitis." (PMID 29503618, 2018). "In the colon, AQP3 is expressed in the epithelial cells where changes in expression were found in response to inflammation, and AQP3-depleted mice experienced impaired recovery after chemical-induced colitis." (PMID 29770164, 2018). "Previously, we showed that the laxative effect of sennoside A is related to decreased aquaporin-3 (AQP3) expression in mucosal epithelial cells due to colonic inflammation." (PMID 29380109, 2018). "In the trinitro-benzene-sulfonic acid-induced colitis of rats, the mRNA and protein expressions of AQP3 and AQP8 were also downregulated in the ileum and colon." (PMID 27589719, 2016). "Moreover, in an in vivo model of colitis, the protective effect of quercetin correlates with a relevant reduction of AQP3 expression level and a lower AQP3-dependent H2O2 transport capability through the plasma membrane." (PMID 39857360, 2024). "This was true when oral glycerol administration could effectively improve survival and reduce the severity of colitis in AQP3-null mice." (PMID 38089478, 2023). "AQP3 knockout mice given dextran sulphate developed more severe colitis compared to wild-type mice." (PMID 35982137, 2022). "Additionally, in 2,4,6-trinitrobenzene sulfonic acid (TNBS)-induced rat colitis model, that resembles human Crohn’s Disease, AQP3 and AQP8 mRNA and protein expression were found downregulated, with aggravated intestine inflammation and injury." (PMID 35187089, 2022). "However, analogously to AQP8, downregulation of AQP3 levels was observed in the colon of Crohn’s disease and ulcerative colitis patients and in drug-induced colitis as the signs of intestinal inflammation and injury progress." (PMID 30463362, 2018). "In AQP3 null mice, dextran sodium sulfate (DSS) induced severe colitis, characterized also by hemorrhage in colon, marked epithelial cell loss and death after 3 days, while wild-type mice showed remarkably less severe colitis, surviving to >8 days." (PMID 29503618, 2018). "Indeed, the AQP3-null mice displayed impaired enterocyte proliferation and developed severe colitis after dextran sulfate treatment, probably due to the impaired glycerol-transporting function." (PMID 27589719, 2016). "AQP3 knock-out mice appear to exhibit more severe epithelialdysfunction in murine DSS colitis." (PMID 25793528, 2015). "Previous study has showed that the AQP3 expression at both mRNA and protein levels was significantly reduced in ileum, proximal colon and distal colon of 2,4,6-trinitrobenzene sulphonic acid-induced rat colitis, indicating its potential roles in the pathogenesis of inflammatory bowel disease." (PMID 38089478, 2023).
colitis (continued). "In addition, AQP3 has been shown to be crucial for enterocyte proliferation, a process induced by the Wnt/β-catenin pathway and mediated by NOX1 : AQP3 knock-out mice showed impaired capacity of proliferation in experimental models of colitis, even leading to significantly reduced mice survival." (PMID 30463362, 2018). "For example, Painong San, a Chinese herbal compound for the treatment of colitis, increased the expression of MUC2 protein in the colon, and P. lactiflora downregulated the expression level of AQP3 in the colon of constipated rats." (PMID 38634140, 2024). "AQP3 and AQP8 have been reported to be down-regulated in rats with colitis and ETEC induced diarrhea." (PMID 37180229, 2023). "AQP3 and AQP8 were detected in the colon of Sprague Dawley rats, and their expression was decreased in 2,4,6-trinitrobenzene sulfonic acid (TNBS)-induced colitis, a model that mimics human Crohn’s disease histopathology." (PMID 33673336, 2021). "Three aquaporins (Aqp3, 8 and 11) were also repressed in TNBS colitis, whereas Aqp9 was upregulated." (PMID 18928539, 2008).
prostate carcinoma (17 papers, 2009 to 2025). A carcinoma that arises from epithelial cells of the prostate gland. "The suppression of AQP3 by siRNA improved the susceptibility of prostate carcinoma cells to cryotherapy." (PMID 38336645, 2024). "However, AQP3 mRNA was detected in both normal and malignant epithelia of human prostate tissues, but not in the mesenchyme, and its suppression improved the susceptibility of prostate cancer cells to cryotherapy." (PMID 38336645, 2024). "Inhibition of AQP3 reduced the intrusiveness of DU-145 and PC-3 prostate cancer cells, which was accompanied by a reduction in MMP3 mRNA levels and function." (PMID 38336645, 2024). "The study also showed that AQP3 upregulates the matrix metalloproteinase 3 expression and its secretion in prostate cancer through activation of the ERK signal pathway." (PMID 36672280, 2023). "Subcellular localization of AQP3 in normal human prostate cells is restricted to the cell membrane whereas in prostate cancer, AQP3 is frequently located in the cytoplasm." (PMID 36672280, 2023). "This mechanistic study revealed that redistribution of AQP3 in prostate cancer occurs through RalA/PKA/cAMP signaling pathways." (PMID 36672280, 2023). "A cDNA microarray-based study demonstrates that prostate cancer cells exhibit overexpression of AQP3 protein." (PMID 36672280, 2023). "has demonstrated that inhibition of AQP3 increases the sensitivity of prostate cancer cells to cryotherapy." (PMID 35847914, 2022). "For prostate cancer (PC), our team demonstrated that AQP3 was primarily expressed in the membranes in the normal prostate epithelia, but in prostate cancer epithelia, AQP3 was often located in the cytoplasm." (PMID 35972604, 2022). "AQP3, located in plasma membranes of human prostate tissue and benign tumors, was found to be internalized in prostate cancer cells, again consistent with a reduction in AQP functionality promoting resistance to apoptosis." (PMID 33499000, 2021). "A much higher AQP3 expression than in normal tissues occurred also in colorectal carcinoma and AQP3 overexpression was reported in prostate cancer cells." (PMID 30893772, 2019). "Inhibition of AQP3 in prostate cancer cells was already proposed as a mechanism that increases the sensitivity to cryotherapy treatment." (PMID 20805891, 2010). "In this study, we investigated the expression and localisation of AQP3 in prostate cancer cells in response to cryoinjury using immunofluorescence staining." (PMID 19513079, 2009). "Interestingly, AQP3 inhibition by HgCl2 can improve the sensitivity of prostate cancer cells to cryotherapy." (PMID 39941100, 2025). "Moreover, it has also been shown that silencing AQP3 improves the effectiveness of cryotherapy for prostate cancer." (PMID 36672280, 2023). "Since the key to the pathological progression of prostate cancer is androgen, we hypothesize that androgen may also be responsible for the tendency of AQP3 to translocate from the cell membrane to the cytoplasm as prostate cancer progresses." (PMID 35972604, 2022). "Here, we show that AQP3 is differentially expressed in cells of a prostate cancer panel." (PMID 33917751, 2021). "Inhibition of AQP3 increases the sensitivity of prostate cancer cells to freezing." (PMID 19513079, 2009). "It was shown that AQP3 protein is expressed in the cytoplasm of the human prostate cancer cells." (PMID 19513079, 2009). "Cryotherapy markedly redistributed AQP3 protein into the plasma membrane of prostate cancer cells." (PMID 19513079, 2009). "Thus, inhibition of AQP3 may be a potential adjunct to cryotherapy for breast and prostate cancer patients." (PMID 35972604, 2022). "Higher levels of JUN, MXD1, and AQP3 were associated with a better OS, and each of the three genes was upregulated by deslanoside, suggesting that JUN, MXD1, and AQP3 could mediate deslanoside’s anticancer effect in prostate cancer cells." (PMID 34830961, 2021).
prostate carcinoma (continued). "OncoPrint data analysis of prostate cancer patients further uncovers the possibilities of AQP1, AQP3, AQP5 and AQP9 being developed as prognostic biomarkers for prostate cancer." (PMID 36672280, 2023). "Ginsenoside was found to inhibit migration of prostate cancer cells in vitro by inhibiting AQP1-dependent pathways, while curcumin was found to inhibit AQP3-mediated cancer cell migration in human ovarian cancer cells." (PMID 33499000, 2021). "We analyzed 14 additional genes, including the AR-activated genes PSA, FKBP51, ORM1, STAG, Nkx3.1, FASN, AQP3, KLK2, and UGT2B; the AR-repressed genes DKK and FST; and the castration-resistant prostate cancer AR-regulated genes CDC20, CDK1, and UBE2C." (PMID 22761715, 2012). "Even though AQPs including AQP1, AQP3, AQP5 and AQP9 have exhibited significant roles that contribute to prostate cancer prognosis, very little progress has been made in identifying AQPs as biomarker(s) for their use in prostate cancer." (PMID 36672280, 2023). "Studies on structural and functional assessment highlight a strong biological relationship between AQPs protein expression, localization, and key biological functions in normal and prostate cancer tissues, where aberrant AQP1, AQP3 and AQP5 expression correlate with tumorigenesis and metastasis." (PMID 36672280, 2023). "We showed clearly that increased sensitivity to cryoinjury was specific to AQP3 knockdown in DU145 and PC-3 cells indicating that the AQP3 gene product may play a role in protecting prostate cancer cells from cryoinjury." (PMID 19513079, 2009).
atopic dermatitis (15 papers, 2012 to 2024). "When the expression level of AQP3 was elevated, impaired barrier integrity and increased pro-inflammatory cytokine production ensued, mimicking the pathological conditions in Notch deficient mice and in atopic dermatitis." (PMID 24260356, 2013). "When cells are exposed to inflammatory or high osmolarity conditions, cellular AQP3 expression is upregulated in response to stress, as is the case in aged or atopic dermatitis skin." (PMID 34799820, 2022). "AQP3 plays a role in hydration in epidermis, and the expression of AQP3 is changed in skin diseases such as atopic dermatitis and psoriasis." (PMID 34471155, 2021). "In fact, strong expression of AQP3 was detected in both the stratum basale and the stratum spinosum in acute and chronic atopic eczema, although epidermal AQP3 was expressed weakly and mainly found in the stratum basale in the case of normal condition." (PMID 28170435, 2017). "Increased expression of AQP3 has been reported in atopic dermatitis, one of the most common inflammatory skin diseases." (PMID 24260356, 2013). "In atopic dermatitis, tumour necrosis factor-α, which is secreted by keratinocytes, increases the production of chemokine CCL17, causing an increase in the AQP3 expression level." (PMID 22315629, 2012). "In addition, the up-regulation of AQP-3 is known to be involved in proliferative skin lesions such as atopic dermatitis or skin squamous cell carcinoma." (PMID 28813533, 2017). "AQP3 expression increases in patients with atopic dermatitis." (PMID 22315629, 2012). "We showed that elevated expression of AQP3 led to a reduced expression of differentiation markers, filaggrin in particular and an increased expression of CCL5 and TNFα, two of the most prominent cytokines in atopic dermatitis." (PMID 24260356, 2013). "Moreover, the changes induced by AQP3 mirrors the effect of Notch inhibition, suggesting AQP3 might not play a passive role in the development of atopic dermatitis." (PMID 24260356, 2013).
diabetes (14 papers, 2019 to 2025). "The down-regulation of AQP3 is supposed to be associated with xeroderma observed in diabetes because streptozotocin-induced diabetic mice showed decreased levels of AQP3 with reduced dermal water content." (PMID 33796134, 2021). "It has also been suggested that AQP3 expression is decreased in the skin of diabetic rats, which is associated with impaired wound healing during diabetes." (PMID 34205315, 2021). "Finally, in addition to effects on wound healing, AQP3 down-regulation has also been proposed to underlie the xeroderma (dry skin), which is often observed in individuals with diabetes." (PMID 37242739, 2023). "An in vitro experiment was carried out to examine whether the decreased expression of cutaneous AQP3 observed in diabetes is caused by an increase in blood glucose levels." (PMID 33494453, 2021). "Thus, we consider astaxanthin useful for treating dry skin caused by decreased AQP3 due to factors such as diabetes mellitus and aging." (PMID 32932769, 2020). "To date, it was known that AQP3 constitutes an important molecule in the onset of diabetes; transgenic Aqp3-deficient mice develop nephrogenic diabetes insipidus; changes in the expression of AQP3 in the adipose tissue, liver, or kidneys have been associated with the development of type 2 diabetes." (PMID 31382467, 2019). "Indeed, in vivo studies have indicated that a diabetes-associated reduction in AQP3 levels may contribute to the skin xerosis observed in diabetes." (PMID 36674890, 2023). "However, the association between xeroderma and AQP3 expression in type 2 diabetes, which accounts for the majority of diabetes cases, remains unclear." (PMID 33494453, 2021). "AQP3 is an important protein involved in corneal wound healing and is downregulated in multiple tissues in diabetes." (PMID 41369370, 2025). "HDACs have recently been shown to be upregulated in various tissues in diabetes, whereas AQP3 levels are downregulated; AQP3 has been shown to promote corneal epithelial cell proliferation and migration." (PMID 41369370, 2025). "The importance of changes in AQP3 in wound healing in diabetes has also been demonstrated, using a streptozotocin (STZ)-induced diabetic rat model in which impaired re-epithelialization correlated with reduced AQP3 expression during the wound healing process." (PMID 36674890, 2023). "In particular, we used db/db mice as a model of type 2 diabetes to examine changes in the dermal water content and cutaneous AQP3 expression with the development of diabetes." (PMID 33494453, 2021). "The results to date show that in diabetes, skin AQP3 expression is decreased, and the skin becomes dry." (PMID 31382467, 2019). "An increase in water intake and urine flow has been reported for a rat model of diabetes mellitus, and this was associated with changes in inner‐medullary AQP2, phosphorylated AQP2 and AQP3 expression." (PMID 31691500, 2019). "This downregulation of AQP3 in diabetes could be a potential factor, likely of many, for the delayed corneal wound healing observed in diabetic patients." (PMID 41369370, 2025). "AQP3 expression is downregulated in multiple tissues in animal models of diabetes." (PMID 41369370, 2025). "For example, in HaCaT cells, a cell line derived from human skin epithelial cells, incubation under hyperglycemic conditions did not affect AQP3 expression; however, treatment with TNF-α, the corneal expression of which we found to be increased with diabetes in mice in vivo, decreased AQP3 levels." (PMID 41369370, 2025). "Data in the literature also suggest a role for AQP3 in the effect of diabetes on the skin." (PMID 37242739, 2023). "Our data thus suggest that TLR2 activation and/or AGEs formation in diabetes may be deleterious for wound healing, in part via downregulation of AQP3 protein in this condition." (PMID 36674890, 2023).
diabetes (continued). "Our results suggest that AGEs affected AQP3 protein expression in a dose-dependent manner, with different effects basally versus under conditions of enhanced protein acetylation as has been observed in diabetes." (PMID 36674890, 2023). "However, with prolonged elevations in AGEs levels and RAGE activation, as well as other changes accompanying diabetes (e.g., inflammation and enhanced protein acetylation), AGEs instead down-regulate AQP3 to impair skin wound healing." (PMID 36674890, 2023). "Our findings suggest that TLR2 activation and AGEs may be beneficial for wound healing and skin hydration under normal conditions via AQP3 upregulation, but that these pathways are likely deleterious in diabetes chronically through decreased AQP3 expression." (PMID 36674890, 2023). "It has been reported that AQP3 in the skin is decreased in STZ-induced type 1 diabetic model rats, which may cause delayed wound healing in diabetes." (PMID 33494453, 2021). "On the other hand, the expression level of AQP3 in the kidney is strongly regulated by the antidiuretic hormone vasopressin, and it is known that vasopressin secretion is enhanced and renal AQP3 is increased during diabetes." (PMID 33494453, 2021). "Therefore, it is unlikely that the decreased expression of cutaneous AQP3 observed during diabetes is directly related to an increase in blood glucose levels." (PMID 33494453, 2021). "Given that persistent increases in the blood glucose level lead to increased oxidative stress, the decreased expression of skin Aqp3 in diabetes may be related to a disturbance of circadian rhythms associated with increased oxidative stress." (PMID 31382467, 2019). "The results of this study suggest that skin AQP3 expression decreases in diabetes, which may limit water transport from the vessel side to the corneum side, causing dry skin." (PMID 31382467, 2019). "Therefore, it is possible that the expression level of AQP3 in the skin decreases in diabetes, the transportation of water from the vessel side to the corneum side is limited, and the dermal water content is decreased." (PMID 31382467, 2019). "Then, the mechanism by which the expression level of skin AQP3 varies in diabetes was investigated." (PMID 31382467, 2019). "Therefore, it is possible that the expression levels of Bmal1 and Clock in the skin are decreased in diabetes and that Aqp3 levels are decreased through the decrease in Dbp expression." (PMID 31382467, 2019). "Therefore, a decrease in cutaneous AQP3 may be involved in not only xerosis but also delayed wound healing during diabetes." (PMID 33494453, 2021). "Therefore, the decrease in skin AQP3 expression in diabetes may be involved not only in xeroderma but also in delayed wound healing." (PMID 31382467, 2019). "The results of this study strongly suggest that the regulation of AQP3 expression in the kidney during diabetes depends on vasopressin rather than inflammatory cytokines." (PMID 33494453, 2021). "Another limitation of our study is the fact that we have not defined the mechanisms by which downregulation of AQP3 might affect wound healing in diabetes." (PMID 36674890, 2023). "In additional in vitro studies, short-term (48 h) hyperglycemic conditions did not alter AQP3 or HDAC expression or activity, although as mentioned in the Introduction, diabetes decreases AQP3 and increases HDAC expression in vivo." (PMID 41369370, 2025).